RNU2-6P (RNA, U2 small nuclear 6, pseudogene)
Gene: Small nuclear RNA gene on chromosome 13 (46,374,401 to 46,374,590, reverse strand). Ensembl gene ENSG00000223336.
Homologues: Orthologues: chimpanzee U2 (99% identical), macaque U2 (95% identical), dog U2 (90% identical), rat LOC120101398 (78% identical). Paralogues in human: U2 (93% identical), U2 (90% identical), RNU2-26P (87% identical), RNU2-2 (87% identical), RNU2-57P (87% identical), RNU2-59P (86% identical), RNU2-4P (86% identical), RNU2-68P (85% identical), RNU2-48P (85% identical), RNU2-3P (84% identical), RNU2-70P (83% identical), RNU2-64P (82% identical), and 67 more.